DES (desmin)
Diseases named in the same sentence as DES in open-access papers (continued):
Sharing a sentence is not in itself a finding about the gene and the disease.
pterygium (1 paper, 2021). A wedge-shaped fibrovascular lesion arising from the bulbar conjunctiva and extending to the cornea. "In addition, analyzing the expression of CALD1, DES, and SMTN, which are three known markers of smooth muscle cells being absent in myofibroblasts, revealed a significant downregulation or comparable expression in pterygium samples when compared to healthy conjunctiva." (PMID 35174178, 2021).
rectal leiomyoma (1 paper, 2024). "Histopathology examination of the polyp revealed smooth muscle proliferation and a positive immunohistochemical profile for desmin, consistent with leiomyomatous nature and a diagnosis of rectal leiomyoma." (PMID 39429256, 2024).
retinoblastoma (1 paper, 2024). A malignant tumor that originates in the nuclear layer of the retina. "Immunohistochemical expression of CD34 and desmin is commonly detected, whereas retinoblastoma gene (Rb) expression is absent." (PMID 39345656, 2024).
rhabdomyolysis (1 paper, 2025). Necrosis or disintegration of skeletal muscle often followed by myoglobinuria. "DES (Desmin) encodes a crucial protein in the structural integrity and function of skeletal muscles and its upregulation is associated with various myopathies associated with muscle weakness and rhabdomyolysis." (PMID 40149400, 2025).
salivary gland tumors (1 paper, 2015). "The use of this technique to improve understanding of salivary gland tumors was initiated in the 1980s with studies of intermediate keratin filaments, vimentin, and desmin." (PMID 26550506, 2015).
spinal cord injury (1 paper, 2022). Penetrating and non-penetrating injuries to the spinal cord resulting from traumatic external forces (e.g., WOUNDS, GUNSHOT; WHIPLASH INJURIES; etc.). "To date, subtypes of pericytes have been identified by various markers, namely the PDGFR-β, Desmin, CD146, and NG2, each of which is involved with spinal cord injury (SCI) repair." (PMID 35296645, 2022).
spinal muscular atrophy (1 paper, 2011). A motor neuron disease that affect the muscles, and characterized by muscle weakness and atrophy resulting from progressive degeneration and irreversible loss of the anterior horn cells in the spinal cord (i.e., lower motor neurons) and the brain stem nuclei. "Immunohistochemical diagnostic procedures reveal that 60% of patients have slight expression of CD34 (vascular origin), 21% have spinal muscular atrophy (epithelial and/or glandular origin), and 8% reveal desmin (muscular origin)." (PMID 21878118, 2011).
steatosis (1 paper, 2020). Increased lipid within the cytoplasm of cells. "The expression profiles of profibrotic genes such as CYGB, ACTA2, PCDH7, DES, COL1A1, and COL1A3 were also significantly up‐regulated in the co‐culture NASH model, when compared with the steatosis model." (PMID 31909357, 2020).
Stroke (1 paper, 2022). Sudden impairment of blood flow to a part of the brain due to occlusion or rupture of an artery to the brain. "Quantification data showed that only 25–30% of blood vessels were desmin-positive in the ipsilateral region after stroke in VEGF-LOF animals." (PMID 35175562, 2022). "CD31-Desmin co-staining demonstrated a high number of blood vessels without pericyte coverage in the VEGF-LOF animals after stroke." (PMID 35175562, 2022).
Ventricular arrhythmia (1 paper, 2023). "DCM associated with sarcomere mutation is characterised by earlier disease onset and prominent ventricular arrhythmias, while SCN5A and desmin gene (DES) mutations present with conduction disease or ventricular arrhythmias as the dominant features." (PMID 36984439, 2023).
virus infection (1 paper, 2023). "In sum, our findings suggest that RABV-M interacts with and hijacks desmin to facilitate the virus infection." (PMID 36851648, 2023). "We found that the IFs component desmin is an interactor with the RABV-M protein that positively regulates the virus infection." (PMID 36851648, 2023). "The overexpression of desmin in BHK-21 cells facilitated virus infection." (PMID 36851648, 2023). "Taken together, these complementary results confirm that desmin interacts with the RABV matrix protein, and positively regulates the virus infection, likely by supporting the efficient virus release." (PMID 36851648, 2023).
X-linked centronuclear myopathy (1 paper, 2013). "Moreover, desmin has been shown to interact with myotubularin, a protein mutated in X-linked centronuclear myopathy (XLCNM or myotubular myopathy)." (PMID 23143191, 2013).
tumor (678 papers, 1987 to 2026). "Using another CAF marker, Desmin, we further show that β1 integrin-deficient tumours also display a marked increase in stromal Desmin+ cells." (PMID 34782719, 2022). "Desmin, originally a smooth-muscle type intermediate filament protein, is expressed in peritumoral fibroblasts, reactive (desmoplastic) stroma, cancer- or tumor-associated fibroblasts, and myofibroblasts." (PMID 27876887, 2016). "This demonstrated that lumen-containing B16 tumor vessels were associated with pericytes that stained positive for both desmin and αSMA, while the majority of small vessels were associated with support cells that expressed only desmin." (PMID 22235379, 2011). "Desmin was expressed in the stromal cell area closely associated with the malignant epithelial glands of the tumor tissue." (PMID 22141345, 2011). "Another tumor in T12-L1 showed diffuse immunopositivity for progesterone receptor and epithelial membrane antigen; the Ki-67 labeling index was about 5%, and smooth muscle-associated tumor was excluded by markers of smooth muscle actin and desmin." (PMID 39792750, 2025). "In addition, desmin, originally a smooth-muscle type intermediate filament protein, is expressed in peritumoral fibroblasts, reactive (desmoplastic) stroma, cancer- or tumor-associated fibroblasts, and myofibroblasts." (PMID 27876887, 2016). "Re-evaluation of the original EMR slides with desmin immunostaining confirmed that the tumor had arisen within a diverticulum, and the true invasion depth was 4000 μm rather than the initially reported 800 μm." (PMID 42011307, 2026). "Immunohistochemical stain showed that tumor cells co-expressed actin, desmin, and caldesmon, whereas S100 protein, CD34, and DOG-1 were negative." (PMID 40951205, 2025). "In cases of suspected CD117-negative GIST, a panel of markers, including DOG1, CD34, S-100, SMA, CD21, ALK, and desmin, should be used to differentiate this tumor from gastric CFTs." (PMID 40356746, 2025). "Immunohistochemical staining revealed positive expression of Myogenin, MyoD1 and Desmin in the tumor cells." (PMID 40520793, 2025). "Immunohistochemically, the tumor cells are typically positive for vimentin, desmin, smooth muscle actin (SMA), and estrogen and progesterone receptors (ER/PR), indicating hormone sensitivity." (PMID 41480427, 2025). "Immunohistochemically, vimentin, SMA, and P16 were diffuse positive in tumor cells, whereas desmin, CK, P40, P63, CK5, HMB45, MyoD1, myogenin, S100, and SOX10 were all negative." (PMID 39872225, 2025). "In the other study, immunohistochemically, the tumor cells express smooth muscle actin (18/20), muscle-specific actin (16/20), fibronectin (20/20), and desmin (2/20)." (PMID 41394850, 2025). "Immunohistochemical stains showed that the tumor cells expressed α-smooth muscle actin, desmin, and caldesmon, whereas S100 protein, CD34, and DOG-1 were negative." (PMID 40951205, 2025). "The tumor lacks intact glandular tissue but contains numerous desmin-positive cells, which also clearly express xCT." (PMID 39869598, 2025). "Later, the intercalated duct cell origin was reported because tumor cells co-expressed cytokeratin, vimentin, and desmin." (PMID 41322839, 2025). "On Immunohistochemistry (IHC), tumor cells show positivity for vimentin, with variable reactivity for actin, desmin, and CD34." (PMID 40092021, 2025). "In accordance with myofibroblastic differentiation of the tumor, positive staining for smooth muscle actin, desmin, vimentin, and CD34 is typically observed." (PMID 40797454, 2025). "Immunohistochemically, the tumor cells are positive for desmin and exhibit heterogeneous nuclear staining for myogenin and MYOD1." (PMID 40282503, 2025).
tumor (continued). "Several muscle cell markers such as vimentin, SMA, and desmin can be used to identify the tumor originating from mesenchymal tissues as an auxiliary diagnosis." (PMID 40224630, 2025). "Immunohistochemistry: the tumor cells expressed Myogenin (11/13), Desmin (13/13), MyoD1 (12/13) and Myoglobin (5/9)." (PMID 40161378, 2025). "Tumour cells were strongly positive for Iba1, desmin and CD204, weakly positive for SMA, and negative for CD31." (PMID 39814065, 2025). "The SMA (Smooth Muscle Actin) and Desmin are both myogenic markers, which can strongly confirm the smooth muscle origin of the tumor cells." (PMID 41573634, 2025). "The results revealed the presence of desmin (DES) in the majority of tumor cells and the focal expression of myogenin (MYOG) and MYOD1." (PMID 41373578, 2025). "Immunohistochemically, vimentin, smooth muscle actin (SMA), and P16 were diffuse positive in tumor cells, whereas desmin, cytokeratin (CK), P40, P63, CK5, HMB45, MyoD1, myogenin, S100, and SOX10 were all negative." (PMID 39872225, 2025). "DSRCT is characterized by desmin-positive small round tumor cells, surrounded by desmoplastic connective/fibrous tissue which we also observed in our patient samples." (PMID 39411551, 2024). "Tumour and stromal regions are also segmented on desmin images using the same DLM by registering the 2 cores together, thereby moving the stromal region segmented on the SMA image to the desmin image." (PMID 38186746, 2024). "The tumor morphology was suggestive of HGESS with variable expression of desmin, ER, PR, AE1/3 and cyclin D1." (PMID 39196362, 2024). "Most tumor specimens showed positivity for desmin, smooth muscle actin (SMA), vimentin, and caldesmon." (PMID 39329869, 2024). "The Panc02 tumor was grown as a dense mass of ZO–1+ tumor cells, surrounded by a dense stromal tissue, mainly composed of Collagen I, Desmin and αSMA+ cells." (PMID 38338669, 2024). "Despite this variation for GFAP and synaptophysin staining, desmin was positive in a significant percentage of neoplastic cells throughout the neoplasm, with rare cells showing densely eosinophilic cytoplasm or elongation." (PMID 39228008, 2024). "Immunophenotyping tests showed positivity of tumor cells for Desmin, Myogenin, MyoD1, Syna, CD56, and ALK." (PMID 38835374, 2024). "The tumor cells in this case diffusely expressed Desmin, Myogenin, and MyoD1, which can lead to the diagnosis of ARMS." (PMID 38835374, 2024). "Immunohistochemically, the tumor cells in our three cases exhibited strong positive staining for desmin, vimentin, ER, and PR." (PMID 38590660, 2024). "In the tumor samples available for immunohistochemistry, heterogeneous desmin positivity (12/13), inconstant MYOD1 (12/13) and myogenin (9/13) expression, and at least partial ALK (9/13) positivity were observed." (PMID 38168093, 2024). "The tumor cells exhibited partial cytoplasmic positive for S-100 and focal cytoplasmic positive for cytokeratin (CK) and desmin, as determined by immunohistochemical staining." (PMID 39612400, 2024). "Utilizing tissue microarrays from 847 patients, it was found that specific alterations in tumor stromal components, particularly a decrease in desmin and smooth muscle α-actin, were independently predictive of recurrence-free survival." (PMID 38791950, 2024). "Tumor cells were strongly positive for CD10, estrogen receptor, and progesterone receptor, whereas, a few tumor cells in an area of epithelial-like configuration were positive for Desmin." (PMID 39121276, 2024). "Desmin is an intermediate filament protein expressed in vascular smooth muscle, and tumor angiogenesis was observed by using a fluorescence localization assay of Desmin to assess the vascular density of B16F10 tumor sections." (PMID 37446286, 2023). "By immunohistochemistry, the tumor cells showed retained INI-1 expression, focal CD10 expression, and loss of BRG1, CK-pan, synaptophysin, desmin, and ER expression." (PMID 37194064, 2023).
tumor (continued). "Immunohistochemical investigation shows positivity for estrogen receptor (ER), progesterone receptor (PR), desmin, smooth muscle actin, and vimentin; some tumours are also CD34-positive." (PMID 36902513, 2023). "After determining the tumor cells by desmin, marking intact glandular tissue with cytokeratin 7 (CK7) and excluding macrophages by CD68, the distribution and localization of GALNT14 was investigated." (PMID 37671061, 2023). "Immunohistochemistry reveals tumor cells’ reactivity to vimentin, desmin, actin, myoglobin, MyoD1, and myogenin." (PMID 36777814, 2023). "Immunohistochemically, the tumor cells were positive for desmin, MYOD1 and SMA, focally positive for myogenin, while negative for h-caldesmon, SOX10 and S100P." (PMID 35642345, 2023). "Desmin expression was present in the majority of evaluated tumors (9/12, 75%), which ranged from rare scattered cells to diffuse strong labeling of all tumor cells in a small number of the PLAGL2-amplified cases." (PMID 36437415, 2023). "Immunohistochemically, the tumor cells are immunoreactive for cytokeratins and desmin and show strong nuclear expression for WT1 (C terminus) and harbor a distinctive EWSR1-WT1 fusion in the molecular pathology." (PMID 37518334, 2023). "The tumor cells showed strong diffuse cytoplasmic immunopositivity for myoglobin and vimentin, and focal staining for desmin." (PMID 37649059, 2023). "We identified an elevated Ki-67 proliferative index, vascular and pericyte markers, CD31 and desmin in the tumor edge as compared to the tumor core." (PMID 37752585, 2023). "Immunohistochemistry results showed positivity for TLE1, EMA, BCL-2, CKH, CK18, and Kiel-67 (in 46% of cells) in some regions of tumor cells; and negativity for Desmin, CD34, S-100, and CD117 in tumor cells." (PMID 38013382, 2023). "To differentiate this tumor from other tumors of different origins, we have done immunohistochemical staining by desmin, S-100 and CD34." (PMID 36609451, 2023). "PAK1 protein expression levels have been found to correlate positively with αSMA and Desmin in pancreatic stellate cells (PSCs), which stimulate angiogenesis and facilitate tumour extravasation." (PMID 38067120, 2023). "Immunohistochemistry demonstrated partial, patchy desmin staining and weak heterogonous neuron-specific enolase immunoreactivity of tumor cells, but a focal staining for Melan-A." (PMID 35501497, 2023). "Transnasal endoscopic biopsy revealed fragments of sclerosed tissue containing pleomorphic tumour cells with areas of tumour necrosis that stained positive for Desmin, CD56 and Myo D1." (PMID 35155025, 2022). "The IHC studies showed that the tumor cells were mostly positive for vimentin, desmin, estrogen receptors (ER) and progesterone receptors (PR), while weak expression of SMA was also noticed." (PMID 36262943, 2022). "Actin staining was seen in the walls of the vessels and bundles of smooth muscle cells encompassing the tumour; desmin staining was observed in the bundles of smooth muscle cells." (PMID 35906668, 2022). "PTD 25 was derived from the pinnal tumor in mouse #1729, and shows desmin positivity like the original tumor." (PMID 35468745, 2022). "This study shows that circulating tumor cells (CTCs) are detectable in blood and bone marrow of patients with rhabdomyosarcoma and that most CTCs express the mesenchymal marker desmin." (PMID 35212153, 2022). "We demonstrated the presence of CTCs and DTCs in blood and bone marrow of pediatric RMS patients by using a reliable platform as CellSearch system implemented with desmin marker to detect mesenchymal circulating tumor cells." (PMID 35212153, 2022). "By immunohistochemistry, DAM is typically a desmin-positive myofibroblastic tumour with variable expression of HMGA2, α-smooth-muscle actin (from 27% to 95% of cases) and CD34 (from 17% to 50%)." (PMID 35204448, 2022). "Immunohistochemically, the tumor cells showed diffuse positivity for desmin, CD56, CD57, EMA and cyclin D1." (PMID 35626339, 2022).